MEFV (MEFV innate immunity regulator, pyrin)
Diseases named in the same sentence as MEFV in open-access papers (continued):
Sharing a sentence is not in itself a finding about the gene and the disease.
Crohn disease (5 papers, 2019 to 2025). A gastrointestinal disorder characterized by chronic inflammation involving all layers of the intestinal wall, noncaseating granulomas affecting the intestinal wall and regional lymph nodes, and transmural fibrosis. "MEFV variants, and particularly the M694V polymorphism, are also associated with both ulcerative colitis and Crohn’s disease in Turkish patients, suggesting a particular role for MEFV in gut mucosal inflammation." (PMID 30946743, 2019).
Erythema (5 papers, 2018 to 2023). Redness of the skin, caused by hyperemia of the capillaries in the lower layers of the skin. "Collectively, these results led us to conclude that age at FMF onset, erysipelas-like erythema, and exon 10 mutation in the MEFV gene are independent factors associated with musculoskeletal manifestation." (PMID 30458853, 2018). "Although this differs from some previous reports, our analyses also revealed that the absence of MEFV exon 10 mutations, later onset, and the presence of erysipelas-like erythema were significantly associated with musculoskeletal manifestations." (PMID 30458853, 2018). "FMF is characterized by periodic episodes of inflammation with fever, polyserositis, and occasionally with recurrent non-erosive monoarthritis or erysipelas-like erythema, all of which are due to autosomal recessive mutations of the Mediterranean fever (MEFV) gene." (PMID 35629299, 2022).
IgA vasculitis (5 papers, 2014 to 2025). "The aim of the study is to investigate the frequency and clinical significance of MEFV mutations in Egyptian children with Henoch-Schonlein purpura (HSP)." (PMID 25232290, 2014). "MEFV gene mutations can drive adaptive and immune responses through innate immune activation and may have an impact on the course of IgA vasculitis." (PMID 40195185, 2025).
multiple sclerosis (5 papers, 2016 to 2025). A progressive autoimmune disorder affecting the central nervous system resulting in demyelination. "Neurological manifestations and the co-occurrence of multiple sclerosis (MS) have been reported in patients with autoinflammatory diseases (AID) and variants of the NLRP3-, MEFV-, or TNFRSF1A gene." (PMID 32563262, 2020).
rheumatic disease (5 papers, 2013 to 2020). "To conduct a sensitivity analysis, we excluded patients with exon 10 mutation in the MEFV gene and patients with rheumatic disease, and reanalyzed the clinical and genetic characteristics among the YOFMF, AOFMF and LOFMF patients." (PMID 30458853, 2018). "It is tempting to speculate that, after the development of rheumatic diseases, the presence of an MEFV mutation modulates the clinical phenotype or contributes to the occurrence of FMF." (PMID 27473114, 2016). "It has been reported that the MEFV gene mutations can be a risk for rheumatic diseases such as AOSD and BD, and can modify clinical phenotypes of rheumatic diseases such as RA and SLE." (PMID 30458853, 2018). "Cabrera-Villalba concluded that in a number of patients with Palindromic Rheumatism MEFV gene mutations can be observed, but this mutation is not likely to be related to the pathogenesis of the disease." (PMID 31171010, 2019). "Peleg suggests the possible role of MEFV gene in different rheumatic disease other than FMF, accordingly RSH could be considered as a MEFV gene related arthritis." (PMID 31171010, 2019).
AIDS (4 papers, 2013 to 2023). A syndrome resulting from the acquired deficiency of cellular immunity caused by the human immunodeficiency virus (HIV). "A substantial contribution to the diagnosis derives from both the consideration of ethnicity and genotype analysis related to MEFV, MVK, TNFRSF1A, NLRP3, NLRP12, PSTPIP1, IL1RN, CARD15/NOD2, and PSMB8, which are the genes responsible for the syndromes collectively termed AIDs." (PMID 23971037, 2013).
colitis (4 papers, 2009 to 2023). Inflammation of the colon. "They suggested that in populations with a high background of the carrier rate of MEFV variants, IBD patients should be screened for MEFV gene mutations, especially those diagnosed with determinate colitis." (PMID 38410520, 2023). "Several studies have illustrated a correlation between human MEFV mutation and paediatric colitis or IBD, among which IBD complicated with FMF is quite common." (PMID 35373402, 2022). "We therefore explored whether MEFV expression was regulated in IBD experimental models of colitis and whether MEFV variants were associated with CD and/or UC susceptibility." (PMID 19784369, 2009). "To further support our candidate gene selection, we first evaluated MEFV expression in different models of experimental colitis." (PMID 19784369, 2009).
cryopyrin-associated periodic syndrome (4 papers, 2017 to 2025). Cryopyrin associated periodic syndrome (CAPS) defines a group of autoinflammatory diseases, characterized by recurrent episodes of systemic inflammatory attacks in the absence of infection or autoimmune disease. "The best known HRF are Familiar Mediterranean Fever (FMF), Cryopyrin-Associated Periodic Syndrome (CAPS), TNF-receptor associated periodic fever syndrome (TRAPS) and Mevalonate-Kinase Deficiency (MKD), caused by mutations in MEFV, NLRP3, TNFRSF1A and MVK genes, respectively." (PMID 29047407, 2017).
lupus (4 papers, 2013 to 2025). "Mutations in the MEFV gene have been previously reported in lupus in various studies including M694V, M680I, V726A, and E148Q, but to date, no A744S mutation has been reported in association with lupus." (PMID 39588206, 2024). "Of note, the number of MEFV variants inversely associated with the risk of lupus nephritis in patients with SLE, underscoring the protective effects of MEFV variants." (PMID 40692783, 2025). "Our results provide compelling evidence for the protective role of MEFV variants, including the E148Q variant, in shaping the clinical trajectory of SLE; MEFV variants may mitigate the severity of lupus nephritis." (PMID 40692783, 2025). "Our findings suggest that MEFV variants, particularly the E148Q variant, may play a protective role against lupus nephritis in Japanese patients with SLE by modulating immune responses." (PMID 40692783, 2025). "Based on the kidney pathology in lupus-prone MRL/lpr mice, the severity of lupus nephritis was reduced in mice carrying the human MEFV E148Q variant." (PMID 40692783, 2025). "In particular, the E148Q variant in the MEFV exon 2 may prevent the development of lupus nephritis in adult patients with SLE." (PMID 40692783, 2025). "Our clinical findings demonstrate a significantly lower prevalence of lupus nephritis in SLE patients carrying MEFV variants compared with non-carriers." (PMID 40692783, 2025). "The number of MEFV variants, but not low CH50 or anti-dsDNA antibody positivity, was significantly associated with lupus nephritis in patients with SLE (odds ratio 0.351, P = 0.03)." (PMID 40692783, 2025).
melanoma (4 papers, 2005 to 2024). A malignant, usually aggressive tumor composed of atypical, neoplastic melanocytes. "For example, CASP4, NLRP1, MEFV, IL18, and NINJ1 correlated positively with GSDMD in metastatic melanoma patients but not in primary melanoma patients." (PMID 38229080, 2024).
plague (4 papers, 2022 to 2025). Plague is a severe bacterial infection caused by the gram-negative bacterium Yersinia pestis. "The crucial role of the pyrin inflammasome in the response to pathogens inducing toxin release (such as Y. pestis) led to the fascinating hypothesis of a possible selective advantage for individual carriers of MEFV causative during plague times." (PMID 37298536, 2023). "Indeed a plague endemic could pose a rapid selection for MEFV variants introduced to Middle Eastern-derived populations early on25." (PMID 36076017, 2022). "Similarly, high frequency of MEFV variants in Middle Easterners and Ashkenazi Jews have been proposed to protect against Yersinia pestis infections, CFTR and GJB2 variants against diarrhea, and CYP21A2 variants have been hypothesized to decrease mortality from pneumonia." (PMID 40162233, 2025).
rheumatoid arthritis (4 papers, 2010 to 2023). A chronic, systemic autoimmune disorder characterized by inflammation in the synovial membranes and articular surfaces. "The aim of this study is to show whether MEFV mutations will be involved in the pathogenesis of RA, to explore the frequency of these mutations and to study the genotype-phenotype correlation between mutations in this gene and a cohort of Moroccan patients with rheumatoid arthritis (RA)." (PMID 35480407, 2022). "His history, physical examination and laboratory findings were negative for rheumatoid arthritis and FMF patients (rheumatoid factor and MEFV gene mutation were negative, respectively)." (PMID 20591157, 2010).
coronary artery disease (3 papers, 2018 to 2021). "Previous investigation had confirmed that MEFV (MEFV innate immuity regulator, pyrin) play critical roles in ischemic heart disease, but this gene might be essential for progression of T1D in patients with ischemic heart disease." (PMID 33827531, 2021).
enthesitis (3 papers, 2016 to 2022). Inflammation at the site of insertion of ligaments, tendons, and other fibrous structures into bone. "However, analysis of several mutations in the MEFV gene showed a significant association of M694V mutation with enthesitis." (PMID 28044082, 2016).
multiple myeloma (3 papers, 2014 to 2024). "High frequencies of inherited variants in the Mediterranean fever (MEFV) gene have been identified in patients with multiple myeloma (MM)." (PMID 25202401, 2014).
pharyngitis (3 papers, 2019 to 2022). Inflammation of the throat most often caused by viral and bacterial infections. "However, for the personal and familial history of monthly recurrent attacks of fever, pharyngitis, abdominal pain, the genetic study of MEFV was performed and demonstrated 3 heterozygous mutations of MEFV (E148Q, P369S, R408Q)." (PMID 31627741, 2019).
Renal amyloidosis (3 papers, 2009 to 2017). A form of amyloidosis that affects the kidney. "We have described a case of renal amyloidosis secondary to refractory SJIA in a carrier of the E148Q mutation in the MEFV gene." (PMID 28499374, 2017). "All 12 common mutations in the MEFV gene were analyzed and the M694V variant was found to be associated with an adverse FMF clinical outcome in the Armenian-American population, which manifested as earlier onset of disease, increased severity of disease, and renal amyloidosis." (PMID 26759267, 2015).
Spondyloarthritis (3 papers, 2018 to 2025). "We investigated whether polymorphisms (SNPs) in the promoter region of TNFA, or in the autoinflammatory TNFRSF1A and MEFV genes, concur with HLA-B27 in enhancing the risk of Spondyloarthritis (SpA) and/or in predicting the response to anti-TNFα treatment." (PMID 29579081, 2018).
arthropathy (2 papers, 2019 to 2020). Any disorder of the joints. "In our opinion, an idiopathic relapsing periodic arthritis in children with exclusively hip involvement (RSH) is a MEFV gene related arthropathy." (PMID 32778116, 2020). "An idiopathic relapsing periodic arthritis in children with exclusively hip involvement is a MEFV gene related arthropathy; whereas with various joint attacks it could be considered as childhood PR." (PMID 31171010, 2019). "In our opinion, an idiopathic relapsing periodic arthritis in children with exclusively hip involvement is a MEFV gene related arthropathy; whereas with various joint attacks it could be considered as childhood PR, a condition that has not been affected by MEFV gene related inflammation." (PMID 31171010, 2019).
asthma (2 papers, 2022 to 2023). "Several studies have suggested that FMF protected against asthma and atopy, potentially due to protective linkage of MEFV with asthma associated genes like IL4RA." (PMID 35281022, 2022).
enterocolitis (2 papers, 2021 to 2023). An inflammatory process affecting the small intestine and colon. "Other authors have proposed the MEFV gene-related enterocolitis concept for some cases diagnosed as IBD-U." (PMID 38410520, 2023). "Based on these clinical cases, we advocated the existence of “MEFV gene-related enterocolitis” within the classification of IBDU." (PMID 33974187, 2021). "The clinical characteristics of MEFV gene-related enterocolitis, including endoscopic findings, remain unclear despite the increasing number of reported cases." (PMID 33974187, 2021).
glioma (2 papers, 2022 to 2023). A benign or malignant brain and spinal cord tumor that arises from glial cells (astrocytes, oligodendrocytes, ependymal cells). "Compared with normal tissues, except for MEFV, NLRP6, NLRP9, RIPK3, and ZBP1, the expression levels of the remaining genes were relatively high in glioma tissues." (PMID 37501725, 2023).
pyoderma gangrenosum (2 papers, 2008 to 2020). An idiopathic, rapidly evolving, and severely debilitating disease occurring most commonly in association with chronic ulcerative colitis. "Mutations involving different autoinflammatory genes (MEFV, NLRP3, NLRP12, NOD2, LPIN2, and PSTPIP1) have been reported in syndromic HS [pyoderma gangrenosum, acne, and hidradenitis suppurativa (PASH) syndrome] as well as in pyoderma gangrenosum (PG), a prototypic neutrophilic dermatosis." (PMID 32425927, 2020).
uveitis (2 papers, 2016 to 2020). An inflammatory process affecting a part of or the entire uvea. "Ocular involvement specifically uveitis was most commonly identified in NLRP3 low-penetrance variants (n = 12; 63%) in comparison to TNFRSF1A- (n = 14; 24%, p = 0.0169) and MEFV variants (n = 6; 18%, p = 0.0141)." (PMID 32563262, 2020).
anaplastic astrocytoma (1 paper, 2021). "In detail, one patient collected tumor specimens in all stages of MT in the present cohort.PRKCQ,PPIF,NRP1,MEFV,GGT1,FAN1, andBTKmutations were found in both DA and anaplastic astrocytoma, whereas mutations ofTBC1D19,ESRRA,DIAPH2,COG6, andCBWD3occurred in HGA." (PMID 34430964, 2021).
anemia (1 paper, 2023). A reduction in the number of red blood cells, the amount of hemoglobin, and/or the volume of packed red blood cells. "The colchicine-non-responders in our study suffered from the severe type of the disease, high ESR, anemia, SAA, CRP, renal stones, lower pyrin concentration, and higher methylation level of the MEFV gene exon 2 than colchicine-responders." (PMID 36661534, 2023).
aseptic meningitis (1 paper, 2020). Inflammation of the membranes surrounding the brain and spinal cord without a bacterial pathogen. "Patients with the incomplete FMF phenotype (mutations in MEFV exons 2 or 3) present with uncommon manifestations such as fever and headache due to aseptic meningitis." (PMID 32765981, 2020).
carditis (1 paper, 2023). "In this study, no statistical difference was found between the presence of MEFV gene mutations, carditis, high anti-streptolysin-O antibody (ASO) levels, and the groups with monoarthritis, polyarthritis, and polyarthralgia (p >0.05)." (PMID 37671203, 2023).
conjunctivitis (1 paper, 2025). Inflammation of the conjunctiva of the eye. "Therefore, the factors, including IL-17A, IL-22, IL-1β, NLRC4, MEFV, and CASP5, detected by ocular surface test in our case should be verified for their usefulness as biomarkers for psoriasis-associated conjunctivitis in clinical studies involving a large number of cases." (PMID 40861543, 2025).
Dengue virus infection (1 paper, 2024). "While the RNASEL gene was shown to play a role during Dengue virus infection, MEFV and MASP2 deficiencies may manifest subclinically, and CFTR deficiency leads to severe outcomes that predominantly involve opportunistic bacterial rather than viral infections." (PMID 39062917, 2024).
depression (1 paper, 2022). "The other demographic and clinical characteristics including age, inbred marriage, smoking, familial history, alcohol, depression and the duration of the evolution of RA does not present a significant correlation between MEFV mutations and patients with RA disease." (PMID 35480407, 2022).
enthesitis related arthritis (1 paper, 2020). "Gülhan’s study showed that certain MEFV mutations may be acting as susceptibility factors for enthesitis related arthritis (ERA)." (PMID 32778116, 2020).
Gitelman syndrome (1 paper, 2026). Gitelman syndrome (GS), also referred to as familial hypokalemia-hypomagnesemia, is characterized by hypokalemic metabolic alkalosis in combination with significant hypomagnesemia and low urinary calcium excretion. "We report a rare case of genetically confirmed Gitelman syndrome (GS) in a Chinese female patient presenting with systemic inflammatory manifestations and a heterozygous MEFV variant of uncertain significance." (PMID 41958666, 2026).
glioblastoma (1 paper, 2022). The most malignant astrocytic tumor (WHO grade IV). "Specifically, while MEFV and STAT3 expression was detected in both glioblastoma cells and immune cells, SARM1 expression level was higher in NPC-like and OPC-like glioblastoma cells than in MES-like, AC-like glioblastoma cells, and other tumor cells." (PMID 35990696, 2022).
Headache syndromes (1 paper, 2020). "Headache syndromes were frequently observed among all AID subgroups w/o MS and most commonly found in patients with MEFV- (n = 14; 74%) followed by TNFRSF1A- (n = 5; 63%) and NLRP3 low-penetrance variants (n = 10, 59%)." (PMID 32563262, 2020).
hereditary periodic fever syndrome (1 paper, 2008). An instance of periodic fever syndrome that is caused by an inherited modification of the individual's genome. "NLRP3, NOD2, MEFV, and PSTPIP1 are the genes responsible for 4 of the syndromes collectively termed hereditary periodic fever syndromes (HPFS)." (PMID 18576390, 2008).
hidradenitis suppurativa (1 paper, 2023). A chronic suppurative and cicatricial disease of the apocrine glands occurring chiefly in the axillae in women and in the groin and anal regions in men. "Moreover, this same genetic variant has been identified as a risk factor for AS, IBD, and severe hidradenitis suppurativa in the Turkish population, indicating that MEFV mutations including M694V may cause predisposition to inflammatory diseases." (PMID 38003572, 2023).
hypercoagulability (1 paper, 2011). "Following the identification and isolation of the MEFV gene, several studies searched for a possible role of MEFV mutations in hypercoagulability." (PMID 21713077, 2011).
Kawasaki disease (1 paper, 2019). A rare inflammatory disease characterized by an acute febrile, systemic, self-limiting, medium-vessel vasculitis primarily affecting children. "Mutations of MEFV can contribute to increase inflammatory expression in other diseases, as Kawasaki disease." (PMID 31627741, 2019).
leukocytoclastic vasculitis (1 paper, 2025). "The reason for MEFV mutation screening was widespread rash in 17 (15.9%), severe systemic involvement in 84 (78.5%), and recurrent leukocytoclastic vasculitis in 6 (5.6%)." (PMID 40195185, 2025).
liver cancer (1 paper, 2023). An epithelial or non-epithelial malignant neoplasm that arises from the liver. "PLK3, C9orf72, TRIM22, RNF152, FEZ1 and MEFV were dramatically downregulated in liver cancer patients, but upregulated by CTD treatment in HCC cells." (PMID 38017425, 2023). "Among them, TOP2A, CENPF, MEFV and C9orf72 directly affect the prognosis of patients with liver cancer." (PMID 38017425, 2023). "Therefore, MAPT, TOP2A, CENPF and MEFV were identified as hub genes of CTD targets that regulate autophagy and also sever as oncogenes or tumour suppressor genes to affect the prognosis of patients with liver cancer." (PMID 38017425, 2023).